SYT14 (synaptotagmin 14)
Description:
May be involved in the trafficking and exocytosis of secretory vesicles in non-neuronal tissues. Is Ca(2+)-independent.
Synonyms: SytXIV; FLJ34198; SCAR11
Tractability: Antibody: UniProt predicts a signal peptide or a membrane-spanning region.
Safety:
Unwanted effects reported when the protein is acted on. In parentheses: how it was acted on, where the effect was seen, and who reports it.
liver injury (source: ClinPGx)
Gene: Protein-coding gene on chromosome 1 (209,900,923 to 210,171,389, forward strand). Ensembl gene ENSG00000143469.
Subcellular location: Membrane
Subcellular location (Human Protein Atlas): Vesicles
Gene Ontology:
Molecular function: phospholipid binding; identical protein binding
Cellular component: membrane
Genetic constraint (gnomAD): Loss-of-function variants: 32 observed, 77.79 expected, observed/expected ratio (o/e) 0.41, 90% interval 0.31 to 0.55. The upper end of that interval is the gene's LOEUF score, 0.55, which puts it in group 2 of 6, group 1 being the genes least tolerant of losing a copy. Missense variants: 791 observed, 1,040.3 expected, observed/expected ratio (o/e) 0.76, 90% interval 0.72 to 0.81. Synonymous variants: 298 observed, 360.15 expected, observed/expected ratio (o/e) 0.83, 90% interval 0.75 to 0.91.
Homologues: Orthologues: guinea pig SYT14 (96% identical), chimpanzee SYT14 (90% identical), macaque SYT14 (89% identical), dog SYT14 (88% identical), pig SYT14 (86% identical), rat Syt14 (84% identical), mouse Syt14 (80% identical), tropical clawed frog syt14 (72% identical), zebrafish syt14a (71% identical). Paralogues in human: SYT16 (43% identical), SYT10 (18% identical), SYT6 (18% identical), SYT3 (18% identical), RPH3A (18% identical), SYT15 (18% identical), SYT15B (18% identical), SYT9 (17% identical), SYTL4 (17% identical), SYT17 (17% identical), SYT7 (16% identical), SYT4 (16% identical), and 19 more.
Diseases named in the same sentence as SYT14 in open-access papers:
SYT14 is named in the same sentence as 15 diseases in open-access papers, as found by Europe PMC text mining. Sharing a sentence is not in itself a finding about the gene and the disease. The quoted sentences say what the papers report.
glioma (5 papers, 2020 to 2023). A benign or malignant brain and spinal cord tumor that arises from glial cells (astrocytes, oligodendrocytes, ependymal cells). "The function of SYT14 in human cancer is unclear, it has been reported that RNAi-mediated SYT14 knockdown inhibits the growth of human glioma cell line." (PMID 34322156, 2021). "Glioma cells with low SYT14 (Synaptotagmin 14) expression were observed to suppress the proliferation capacity." (PMID 34987577, 2021). "RNA‐mediated SYT14 knockdown can inhibit proliferation and colony formation and promote apoptosis of glioma cells." (PMID 33108691, 2020). "SYT14 is a membrane-trafficking protein that can promote the growth of human glioma cells." (PMID 37324492, 2023).
Ataxia (2 papers, 2020 to 2021). Ataxia refers to impaired coordination of voluntary muscle movement. "Additionally, Doi and colleagues reported a homozygous missense mutation of the SYT14 in a Japanese family with psychomotor retardation and cerebellar ataxia." (PMID 34947986, 2021).
absence seizures (1 paper, 2020). "Since SYT14 is implicated in absence seizures, these genetic findings can be related with the JME phenotype, which is characterized by the existence of absence seizures." (PMID 32973469, 2020).
autosomal recessive spinocerebellar ataxia (1 paper, 2021). "SYT14 mutations have been reported to cause autosomal recessive spinocerebellar ataxia with psychomotor retardation in humans, but little else is known about the protein." (PMID 33619613, 2021). "The only link to SYT14 function comes from a single report suggesting Syt14 mutations may cause autosomal recessive spinocerebellar ataxia in humans." (PMID 33619613, 2021).
gastric cancer (1 paper, 2021). A primary or metastatic malignant neoplasm involving the stomach. "1.The expressions of SYT4, SYT9 and SYT14 were up-regulated in gastric cancer (GC)." (PMID 34229539, 2021).
cancer (3 papers, 2021 to 2023). A tumor composed of atypical neoplastic, often pleomorphic cells that invade other tissues. "According to increasing evidence on the correlations between immune cell infiltration and prognosis in cancer, we utilized the TIMER database to evaluate the association between the expressions of SYT4, SYT9, and SYT14 and immune cell infiltration." (PMID 34229539, 2021).
tumor (3 papers, 2021 to 2023). "The expression of GNG8, MYO1H, and TNFRSF13B was significantly down-regulated, while the expression of SYT14 and FOXA2 was significantly up-regulated in the samples with higher tumor stage, the samples with high risk had lower overall survival rates." (PMID 34322156, 2021). "Furthermore, we found that several upregulated genes in those enhanced subclones, including SYT14, CREB5, and ABCA1, were associated with drug resistance and tumor proliferation in previous reports." (PMID 37324492, 2023). "Moreover, the expression of GNG8, MYO1H, and TNFRSF13B was significantly down-regulated, while the expression of SYT14 and FOXA2 was significantly up-regulated in the samples with higher tumor stage." (PMID 34322156, 2021).
neurodevelopmental disorder (1 paper, 2021). A behavioral and cognitive disorder with onset during the developmental period that involves impaired or aberrant development of intellectual, motor, or social functions. "Together, these studies indicate that dysfunction of SYT14 might be involved in neurodevelopmental disorders." (PMID 34947986, 2021).
SYT14 also shares sentences with these, for which no sentence is quoted: bipolar disorder (2 papers); Cerebral atrophy (2); developmental delay (2); cerebellar ataxia (1); dental caries (1); periodontitis (1); schizophrenia (1).